GLI3 (GLI family zinc finger 3)
Diseases named in the same sentence as GLI3 in open-access papers (continued):
Sharing a sentence is not in itself a finding about the gene and the disease.
microcephaly (5 papers, 2018 to 2024). A congenital or acquired developmental disorder in which the circumference of the head is smaller than normal for the person's age and sex. "Our findings imply a potential strategy and possibility to treat Gli3-deficiency induced macrocephaly by silencing microcephaly-pathogenic gene miR-7." (PMID 30210296, 2018). "From these genes, four are associated either with microcephaly (CUL3 [MIM: 603136]) or macrocephaly (CDH2 [MIM: 114020], GLI3 [MIM: 165240], and WNT5A [MIM: 164975])." (PMID 39168120, 2024). "We used coding variation, transcript and protein levels, to uncover 12 genes likely mediating the effect of these variants, including GLI3 and CDK6 that affect cranial synostosis and microcephaly, respectively." (PMID 36415660, 2022). "We observed one single m6A site near the stop codon in 7 microcephaly-related E-SMRs, including Brca2, Cep152, Ddx11, Nde1, Kif14, Stil and Cdk5rap2, 3 polymicrogyria-related E-SMRs (Eomes/Tbr2, Pax6 and Foxp2), and 3 megalencephaly-related E-SMRs (Gli3, Ccnd2 and Kif7)." (PMID 32992647, 2020).
non-small cell lung carcinoma (5 papers, 2016 to 2023). A group of at least three distinct histological types of lung cancer, including non-small cell squamous cell carcinoma, adenocarcinoma, and large cell carcinoma. "SET7 lysine 436 (K436) and -K595 dependent methylation of GLI3-FL regulates cell viability and colony formation of the non-small cell lung cancer (NSCLC) cell line A549 as well." (PMID 32245491, 2020). "Set7-mediated methylation of Gli3 at the K436 and K595 sites increases the stability of Gli3 and its ability to bind to DNA, thereby activating Shh signaling and contributing to the development of non-small cell lung cancer." (PMID 37144123, 2023). "Furthermore, we demonstrate that this Set7 mediated Gli3 methylations contribute to the tumor growth and metastasis in non-small cell lung cancer in vitro and in vivo." (PMID 27146893, 2016). "Furthermore, functional experiments indicate that the Gli3 methylation contributes to the tumor growth and metastasis in non-small cell lung cancer in vitro and in vivo." (PMID 27146893, 2016).
ovarian carcinoma (5 papers, 2013 to 2025). A malignant neoplasm originating from the surface ovarian epithelium. "Bioinformatics analysis predicted miR-506 as a potential regulator of Gli3 expression, and our results confirmed that 6-gingerol upregulates miR-506, which in turn suppresses Gli3 expression and induces ovarian cancer cell apoptosis." (PMID 41018112, 2025). "Our results showed that upregulation of miR-506 reduces ovarian cancer cell proliferation by targeting the transcription factor Gli3." (PMID 41018112, 2025). "Given that GL13 knockdown inhibits the growth and migration of ovarian cancer cells, we investigated Gli3 expression in 6-gingerol-induced apoptosis." (PMID 41018112, 2025). "Our study identified the miR-506/Gli3 signaling axis as a key pathway through which 6-gingerol induces apoptosis in ovarian cancer cells." (PMID 41018112, 2025). "In summary, Our findings demonstrate that 6-gingerol induces ovarian cancer cell apoptosis through miR-506-mediated Gli3 suppression, providing an alternative to conventional Bax/Bcl-2-targeting approaches." (PMID 41018112, 2025). "By inhibiting Gli3 expression, miR-506 promotes apoptosis in human ovarian cancer cells." (PMID 41018112, 2025). "We analyzed the mRNA expression profiles of HH-related genes—SHH, HHAT, PTCH1, GLI1, GLI2, GLI3, and SUFU—in two ovarian cancer cell lines." (PMID 40565349, 2025). "To assess their potential prognostic value, we analyzed the correlation between the expression levels of the following eight components of the Hedgehog signaling pathway on the progression-free (PFS) and overall survival (OS) in ovarian cancer: SHH, GLI1, GLI2, GLI3, PTCH1, PTCH2, HHAT, and SUFU." (PMID 40565349, 2025). "Knockdown of Gli3 suppresses the proliferation and migration of androgen receptor-positive breast and ovarian cancer cells, which does not occur for androgen receptor-negative cells." (PMID 41018112, 2025). "Using the database Kaplan–Meier plotter, which includes the gene expression and survival data of 1565 ovarian cancer patients, higher expression levels of the genes SHH, PTCH1, PTCH2, and GLI1 displayed better survival correlations, while GLI, GLI3, and SUFU correlated with adverse outcomes." (PMID 40565349, 2025).
glioblastoma (4 papers, 2009 to 2022). The most malignant astrocytic tumor (WHO grade IV). "In glioblastoma, GLI3 was downregulated upon anti-cancer drug treatment." (PMID 32245491, 2020). "In a microarray gene profiling analysis where glioblastoma cell lines DBTRG and U87 were treated with ‘Y15’ in combination with temozolomide, the expression of GLI3 was downregulated." (PMID 32245491, 2020). "One glioblastoma exhibited only a gain for STK31 on 7p15.3 and GLI3 on 7p14.1." (PMID 35361262, 2022).
lung adenocarcinoma (4 papers, 2014 to 2024). A carcinoma that arises from the lung and is characterized by the presence of malignant glandular epithelial cells. "In a study of advanced lung adenocarcinoma, GLI1 mRNA and GLI3 mRNA expression were associated with lower 5-year survival rates in patients." (PMID 38498906, 2024). "The levels of GLI1, GLI2, and GLI3 mRNA expression were measured by quantitative real-time polymerase chain reaction in surgically obtained tissue samples from stage II-IV lung adenocarcinoma patients (n = 102)." (PMID 25103784, 2014). "The present study also provides evidence of the capacity of GLI3 to activate Hh signaling in concert with GLI1 in advanced lung adenocarcinoma." (PMID 25103784, 2014). "Interestingly, some GLI1/GLI3 highly expressing tumors (in this cohort, defined as the upper 15th percentile of patients for each mRNA expression) showed significantly poorer patient prognosis in advanced lung adenocarcinoma." (PMID 25103784, 2014). "As we found considerable impact of GLI1 and GLI3 gene expression on patient survival, this study demonstrates that inhibition of Hh signaling may be a promising drug target for the treatment of advanced lung adenocarcinoma." (PMID 25103784, 2014). "High expression of ACOT1 is related to unfavorable prognosis of gastric adenocarcinoma via increased tumor-promoting protein GLI3, while ACOT8 is demonstrated to be an independent predictor of lymph node metastasis and survival of lung adenocarcinoma." (PMID 33362855, 2020). "Subset analysis of patients with stage III-IV lung adenocarcinoma (n = 71) showed significantly worse clinical outcomes in both the higher GLI1 and GLI3 mRNA expression groups." (PMID 25103784, 2014). "We found that GLI1, GLI2, and GLI3 mRNA were expressed in almost all advanced stage lung adenocarcinoma tissue samples, and strong correlation was observed between GLI1 and GLI3 mRNA expression." (PMID 25103784, 2014). "From our research, no relation between GLI2 mRNA expression and GLI1 mRNA level, GLI3 mRNA level, or patient survival was detected, thus, the role of GLI2 in the pathogenesis of lung adenocarcinoma is still unclear." (PMID 25103784, 2014). "Mutations in RHPN2 (5%), GLI3 (4%) and MRC2 (2%) have not been reported previously as driver genes in lung adenocarcinomas but were recurrently observed in our cohort and are nominated to be significantly mutated." (PMID 26647728, 2015). "Interestingly, some lung adenocarcinoma samples showed relatively high GLI1 and GLI3 mRNA expression, and their expression patterns were considerably correlated." (PMID 25103784, 2014).
Obesity (4 papers, 2015 to 2022). Accumulation of substantial excess body fat. "Our study demonstrates the presence of a 14-3-3ζ-Gli3-p27Kip1 axis that regulates adipocyte differentiation and suggest that targeting components of this axis may be a beneficial therapeutic approach for the treatment of obesity." (PMID 26220403, 2015). "For instance, obesity downregulates SHH signaling, including the expression of GLI1, GLI2, and GLI3." (PMID 31316554, 2019).
Polysyndactyly (4 papers, 2011 to 2024). Polysyndactyly or PPD4 is a form of preaxial polydactyly of fingers (see this term), a limb malformation syndrome, characterized by the presence of a thumb showing the mildest degree of duplication, being broad, bifid or with radially deviated distal phalanx. "In 2020, a report was published suggesting that frameshift mutations of GLI3, ANKUB1, and TAS2R3 might alter protein functions and accelerate the progression of polysyndactyly (PSD), an autosomal dominant genetic limb malformation." (PMID 38871700, 2024).
acute myeloid leukemia (3 papers, 2020 to 2024). Acute myeloid leukemia (AML) is a group of neoplasms arising from precursor cells committed to the myeloid cell-line differentiation. "Downregulation of GLI3 expression mediates chemotherapy resistance in acute myeloid leukemia." (PMID 38498906, 2024).
bladder cancer (3 papers, 2020 to 2025). "The aberrant activation of the SHH signaling pathway exhibits significant heterogeneity in bladder cancer, characterized primarily by dysregulated activation of the Gli transcription factor family (particularly Gli3) and imbalance in non-coding RNA regulation." (PMID 41438986, 2025). "Gli3 expression levels show a positive correlation with pathological grade, depth of invasion, and lymph node metastasis in bladder cancer." (PMID 41438986, 2025). "A significant upregulation of GLI3 in bladder cancer was reported by microarray gene expression profiling." (PMID 32245491, 2020). "GLI3 mRNA expression was significantly upregulated in tissue from bladder cancer patients and there was an inverse correlation between GLI3 and miR-494." (PMID 32245491, 2020). "The abnormal activation of the SHH pathway is primarily mediated through the following mechanisms: microRNA miR-7-5p is significantly downregulated in bladder cancer, where it directly binds to the 3’ untranslated region of Gli3 to inhibit its protein expression." (PMID 41438986, 2025). "miR-7-5p was identified as a negative regulator of GLI3 in bladder cancer." (PMID 32245491, 2020). "GLI3 was shown to be regulated by miR-7-5p in bladder cancer tissue." (PMID 32245491, 2020). "In those studies, a physical interaction between miR-7-5p and GLI3 was identified (GLI3 interaction site: GUCUUCCA), which leads to a negative regulation of GLI3 and to a less cancerous phenotype of bladder cancer cells." (PMID 32245491, 2020).
cleft palate (3 papers, 2012 to 2023). Cleft palate is a fissure type embryopathy that affects the soft and hard palate to varying degrees. "In 2008, Huang’s group correlated GLI3 deficiency with a high incidence of cleft palate, associated with abnormal tongue development, in a murine model." (PMID 36830605, 2023). "Disruption of the function of Shh, Smo, or the transcriptional effectors Gli2 or Gli3, during palatal development each causes cleft palate in the mutant mice, indicating that Shh signaling regulates palate development through Gli mediated transcriptional regulation." (PMID 26745863, 2016). "Patients with PHS and mutations in the GLI3 gene may have also clinical manifestations that overlap the OFD VI-phenotype, namely mesoaxial or postaxial polydactyly and oral findings including additional frenula, tongue hamartomas, and cleft palate." (PMID 22236771, 2012).
Joubert syndrome (3 papers, 2017 to 2022). Joubert syndrome (JS) is characterized by congenital malformation of the brainstem and agenesis or hypoplasia of the cerebellar vermis leading to an abnormal respiratory pattern, nystagmus, hypotonia, ataxia, and delay in achieving motor milestones. "This defective processing of Gli3 with aberrant SHh signaling is similar to that seen in the brains of individuals with Joubert syndrome/Meckel syndrome." (PMID 33960602, 2021).
Macrocephaly (3 papers, 2018 to 2024). Occipitofrontal (head) circumference greater than 97th centile compared to appropriate, age matched, sex-matched normal standards. "Moreover, targeting miR-7 could offer a potential therapeutic way to Gli3-deficiency induced macrocephaly." (PMID 30210296, 2018). "Brain growth disorders as micro- (ASPM, MCPH1) and macrocephaly (NFIX, GLI3) have been highlighted as relevant for the evolution in humans due to the impact in early brain development." (PMID 36550402, 2022).
oral squamous cell carcinoma (3 papers, 2020 to 2024). "GLI3 inhibition decreases stemness, cell proliferation, and invasion in oral squamous cell carcinoma." (PMID 38498906, 2024). "In addition to the involvement of GLI3 in hamartoma, GLI3 plays a role in Oral squamous cell carcinoma (OSCC)." (PMID 32245491, 2020).
rhabdomyosarcoma (3 papers, 2017 to 2022). A rare aggressive malignant mesenchymal neoplasm arising from skeletal muscle. "Previous studies have found that GLI3 is highly expressed in embryonal rhabdomyosarcoma and some alveolar rhabdomyosarcoma, and it is associated with the prognosis of Ewing sarcoma." (PMID 36619306, 2022).
Anosmia (2 papers, 2020 to 2025). An inability to perceive odors. "The patient harboring the GLI3 loss-of-function variant is a 38-year-old male, who presented to medical attention at age 18 years with anosmia and failure to enter puberty." (PMID 31767679, 2020). "Similarly, Gli2/Gli3 mutants, which model disrupted GnRH neuronal migration analogous to Kallmann syndrome, often exhibit early lethality or anosmia that prevent behavioral assessment into adulthood." (PMID 41357796, 2025).
basal cell carcinoma (2 papers, 2007 to 2023). A carcinoma involving the basal cells. "Gli-3 also inhibits Gli-1's ability to upregulate bcl-2 transcription in basal cell carcinoma." (PMID 17505514, 2007).
breast tumor (2 papers, 2011). "The PR gene, PGR, and 3 other genes (GATA3, STC2 and GLI3) are increased in their expression, whereas the expression of 6 genes (AURKA, BUB1, CDC20, MKI67, HJURP, and CENPA) is decreased in PR-positive breast tumors." (PMID 22022496, 2011).
cholangiocarcinoma (2 papers, 2018 to 2021). A carcinoma that arises from the intrahepatic biliary tree (intrahepatic cholangiocarcinoma) or from the junction, or adjacent to the junction, of the right and left hepatic ducts (hilar cholangiocarcinoma). "Furthermore, at the transcriptional level, negative regulation of TRAIL-R1 promotor by GLI3 as well as miR-25-dependent decrease of TRAIL-R1 levels were reported for cholangiocarcinoma cells." (PMID 30064384, 2018). "Both mutation and copy number alterations (CNA) affecting Hedgehog pathway main members, namely GLI1, GLI2, GLI3, SMO, PTCH1/2, SUFU, and DHH, have been observed in mixed cholangiocarcinoma patients with different frequencies." (PMID 34638259, 2021). "GLI1, as in other tumors, was found to promote iCCA survival, growth, and EMT reprogramming, together with GLI3, which directly binds to the promoter of death receptor 4 (DR4), repressing its transcription and thus preventing TRAIL-dependent cholangiocarcinoma cell death." (PMID 34638259, 2021).
colon adenocarcinoma (2 papers, 2021 to 2024). "In addition, GSCALite analysed the correlations between those EMT markers and different pathways in both colon adenocarcinoma (COAD) and rectal adenocarcinoma (READ), and the results indicated that GLI3 had a tight link with EMT compared to other traditional EMT markers." (PMID 33506047, 2021).
diabetic retinopathy (2 papers, 2023 to 2024). "We further demonstrate broader applicability for this SNP and GLI3 genetic variation with other forms of retinal disease characterized by pre-retinal neovascularization, namely diabetic retinopathy." (PMID 37292936, 2023). "We further identify significance of GLI3 variation for pre-retinal neovascular disease and established ROP genetic risk associations using extension analysis within an independent validation cohort consisting of Hispanic individuals with diabetic retinopathy." (PMID 38233474, 2024).
endometriosis (2 papers, 2021 to 2022). The growth of functional endometrial tissue in anatomic sites outside the uterine body. "SHH, SMO, GLI1 and GLI3 expression was strongly increased with clinical stages in the eutopic endometrium, which suggested that the SHH signaling pathway was abnormally activated in endometriosis." (PMID 35933378, 2022).
epilepsy (2 papers, 2023 to 2024). A brain disorder characterized by episodes of abnormally increased neuronal discharge resulting in transient episodes of sensory or motor neurological dysfunction, or psychic dysfunction. "In our cohort, all 4 patients with a GLI3 variant had a gelastic epilepsy-plus phenotype." (PMID 39246740, 2024).
hepatocellular carcinoma (2 papers, 2016 to 2020). A malignant tumor that arises from hepatocytes. "The hepatic level of miR-378a-3p is inversely correlated with the expression of Gli3 in tumour and non-tumour tissues in human hepatocellular carcinoma." (PMID 27001906, 2016). "To investigate the potential role of miR-378a-3p in its clinical implications, we analysed the expression of miR-378a-3p and its target, gli3, in non-tumour and tumour regions of liver tissues obtained from 18 patients with hepatocellular carcinoma (HCC) and advanced fibrosis (stage F3 or F4)." (PMID 27001906, 2016).
Intellectual deficiency (2 papers, 2019 to 2021). "Intellectual deficiency is rare in loss-of-function mutations of GLI3 associated with GCPS syndrome, but is frequently described and correlates with the size of deletion of GCPS-CGS." (PMID 34828280, 2021). "A good prognosis of the patient is frequently reported and the risk of intellectual disability is usually related to the size of the deletions in the GLI3 gene." (PMID 31010437, 2019). "Cases with a chromosomal microdeletion encompassing GLI3 (deletions larger than 1 Mb) are referred to as GPS-CGS, and they typically present with a more complex neurobehavioral phenotype including intellectual disability, severe motor retardation and neurological symptoms." (PMID 34828280, 2021).